HDAC4 (histone deacetylase 4)
Diseases named in the same sentence as HDAC4 in open-access papers (continued):
Sharing a sentence is not in itself a finding about the gene and the disease.
diabetes (16 papers, 2015 to 2025). "Mutations in HDAC4 disrupt the deacetylation of FoxO1, subsequently decrease the β‐cell function including insulin secretion, resulting in diabetes." (PMID 30968599, 2019). "To investigate whether or not cellular translocation of FoxO1 is critically influenced by our diabetes‐associated HDAC4 mutations, we transfected wild‐type and three mutated HDAC4s (p.H227R, p.D234N, p.E374K) into mouse MIN6 β‐cells and examined FoxO1 with immunostaining." (PMID 30968599, 2019). "Regarding hypomethylated DMRs, they involved genes linked to metabolic control of diabetes such as FN3K, RPH3AL and HOX, HDAC4." (PMID 36870961, 2023). "Inhibition of HDAC-4 also restores the acetylation status of nephrin, thereby improving diabetes-induced podocyte injury and renal dysfunction." (PMID 38074159, 2023). "O-GlcNAcylation at Ser642 of histone deacetylase 4 (HDAC4) is cardioprotective in diabetes mellitus." (PMID 36010594, 2022). "All mice were sacrificed at 4 weeks post-injection of naked HDAC4 siRNA, DTsiANp/scramble, DTsiANp/HDAC4 to diabetes mice." (PMID 31690769, 2019). "Cebpb, Hdac4, Ski, Socs1 mRNAs, which are reduced in diabetes and/or insulin resistance, have also demonstrated protective roles in these conditions." (PMID 30369883, 2018). "We also observed alterations in epigenetic modifiers such as HDAC4, whose mutation impairs β-cell function and insulin secretion, leading to a non-autoimmune paediatric diabetes." (PMID 36870961, 2023). "Furthermore, renin instability has been shown to decrease podocyte survival and accelerate diabetes-induced renal damage, while HDAC-4 signaling is involved in renin stability in the progression of diabetes-induced podocyte injury." (PMID 38074159, 2023). "Interestingly, HDAC4 was identified as a central player in diabetes-related podocyte injury." (PMID 40944292, 2025). "Interestingly, we observed that acetylated FoxO1 dramatically increased if cells were exposed to diabetes‐associated HDAC4 mutations, compared to wild‐type HDAC4, while there was no much change in total FoxO1 protein level." (PMID 30968599, 2019). "For example, HDAC4 expression significantly increased in the kidneys in patients with focal segmental glomerulosclerosis, and the upregulation of HDAC2, HDAC4, and HDAC5 was observed in patients with DN and animal models of diabetes." (PMID 40944292, 2025).
Parkinson disease (15 papers, 2013 to 2025). A progressive degenerative disorder of the central nervous system characterized by loss of dopamine producing neurons in the substantia nigra and the presence of Lewy bodies in the substantia nigra and locus coeruleus. "For example, histone deacetylase 4 (HDAC4) was shown to be mislocalized in patient hiPSC-derived dopaminergic neurons modeling Parkinson’s disease, causing downregulation of critical genes." (PMID 32973457, 2020). "Interestingly, HDAC4-positive nuclear inclusions have been associated with pathogenesis of neurological disorders including Lewy bodies in Parkinson’s disease and intra-nuclear inclusions in intra-nuclear inclusion disease." (PMID 33859551, 2021). "For example, mutations in the gene ATP1A3, which is downregulated by HDAC4, cause a rare rapid-onset dystonia-parkinsonism and is linked to altering intracellular calcium levels, which could impact on the ER, the principal intracellular store of calcium." (PMID 30503143, 2019). "Nuclear accumulation of HDAC4 promotes neurodegeneration in Ataxia telangiectasia and Parkinson’s disease." (PMID 39806423, 2025). "For example, histone deacetylase 4 (HDAC4) is shown to be mislocalized in patient iPSC-derived dopaminergic neurons, which model Parkinson’s disease and cause the downregulation of some critical genes." (PMID 34680440, 2021). "Recent literature has shown that TasQ is effective in the modulation of HDAC4 at the concentration of 15 μM in Parkinson’s disease patient iPSC-derived dopamine neurons." (PMID 34445342, 2021). "HDAC4 expression is dysregulated in several neurodegenerative diseases, such as Alzheimer’s and Parkinson’s diseases." (PMID 33670779, 2021). "Treatment of these neurons with compounds that specifically inhibited MAP4K4 action corrected HDAC4 mislocalization and rescued the Parkinson’s disease phenotype." (PMID 32973457, 2020). "Furthermore, there is growing evidence that HDAC4 exerted neurotoxicity by its nuclear accumulation and involvement in both Lewy and Marinesco bodies in models of Parkinson’s disease." (PMID 35625059, 2022). "Moreover, the analysis identified the epigenetic modifier, HDAC4, as a potential target for Parkinson’s disease (PD) treatment." (PMID 33499699, 2021). "In other neurodegenerative conditions like Parkinson's disease (PD), HDAC4 may also be important." (PMID 35814270, 2022). "Finally, these findings may have wider implications as HDAC4 is a component of Lewy Bodies in Parkinson's disease brains and administration of SAHA improved the synaptic plasticity and learning behaviour in an Alzheimer disease model." (PMID 24302884, 2013). "Interestingly, elevated HDAC4 levels have been shown in post mortem HD and FTLD (Frontotemporal Lobar Degeneration) brains and HDAC4 has been described as a component of Lewy Bodies in Parkinson's disease brains and of intranuclear inclusions in the neuronal intranuclear inclusion disease." (PMID 25759639, 2015).
melanoma (14 papers, 2017 to 2025). A malignant, usually aggressive tumor composed of atypical, neoplastic melanocytes. "Using genomic databases, we found that increased levels of HDAC4 were associated with decreased antitumor immune responses, resulting in the reduced overall survival and disease-free survival of melanoma patients." (PMID 40361444, 2025). "The group of melanoma patients with elevated HDAC4 expression exhibited not only poor prognosis but also diminished transcription of T-cell inflamed TME gene signatures and increased DNA methylation of T-cell inflamed TME gene signatures." (PMID 40361444, 2025). "Nevertheless, further analyses using ChIP-seq data, promoter motif enrichment, or histone modification signatures are needed to validate the significance of HDAC4 in melanoma prognosis." (PMID 40361444, 2025). "Overall, these studies highlighted the prognostic value of HDAC4 and indicated that a combination of HDAC4 inhibitor and ICIs would result in a better prognosis for melanoma patients." (PMID 40361444, 2025). "Our studies in the SKCM dataset and the ICI-pretreated melanoma dataset have provided valuable insights into the possible role of HDAC4 in modulating the TME in melanoma." (PMID 40361444, 2025). "The accumulation of DNA damage was confirmed in the second model of HDS, A375 melanoma cells silenced for HDAC4 or knocked-out by CRISPR/Cas9." (PMID 38874468, 2024). "The differential upregulation of these SES-associated genes was confirmed when senescence was induced by depletion of HDAC4 in melanoma cells." (PMID 38874468, 2024). "MC1568 decreases the levels of interleukin-8 and the proliferation of melanoma cells, and has shown potent and specific inhibition of class II HDACs, such as HDAC4 and HDAC5." (PMID 34203519, 2021). "The role of HDAC4 in antagonizing senescence in melanomas was confirmed by RNAi mediated silencing in WM115 cells." (PMID 33966634, 2021). "For example, HDAC1 somatic mutations have been found in 8.3% of dedifferentiated liposarcoma and HDAC4 homozygous deletions are found in 4% of melanoma." (PMID 32158695, 2020). "The expression of four selected genes (MTOR, ABCC1, PLK2 and HDAC4) was validated in nine melanoma cell lines by qPCR." (PMID 28417283, 2017). "We also utilized an ICI-pretreated melanoma cohort to further investigate the role of HDAC4." (PMID 40361444, 2025). "Thus, the current study was designed to determine the impact of the association between T-cell inflamed TME gene signatures and HDACs, with major emphasis on HDAC4 in influencing the efficacy of ICIs in melanoma patients." (PMID 40361444, 2025). "To further strengthen our hypothesis, we next evaluated the effect of HDAC4 in the ICI-pretreated cohort of melanoma patients." (PMID 40361444, 2025). "This indicates that HDAC4 inhibitors may represent a promising strategy to improve the effect of ICIs in melanoma patients." (PMID 40361444, 2025). "Overall, this research shows that a combination of HDAC4 inhibitors and ICIs could result in better melanoma prognosis." (PMID 40361444, 2025). "Overall, these findings suggest that HDAC4 inhibitors could be explored to improve the antitumor immune responses and/or effectiveness of immunotherapy in melanoma patients." (PMID 40361444, 2025). "Importantly, elevated HDAC4 expression was associated with decreased CD8+ T-cells and a decreased ESTIMATE immune score in ICI-pretreated melanoma patients." (PMID 40361444, 2025). "In A375 melanoma cells silenced for HDAC4, we expressed a Dox-inducible version of HDAC4." (PMID 38383514, 2024). "Interestingly, homozygous deletion of HDAC4 has been observed in melanoma cell lines, indicating that HDAC4 can function both as an oncogenic factor and as a tumor suppressor depending on the context." (PMID 39620228, 2024). "As the last model of senescence, we knocked-out HDAC4 in A375 melanoma cells." (PMID 33966634, 2021).
melanoma (continued). "This provided the rationale to extend our studies to explore the impact of HDAC4 expression on the transcription as well as DNA methylation activity of T-cell inflamed TME gene signatures with the goal of correlating their significance with the survival rates of melanoma patients." (PMID 40361444, 2025). "Given that HDAC4 expression negatively impacted T-cell inflamed TME gene signatures, we next sought to determine its effect on the prognosis of melanoma patients." (PMID 40361444, 2025). "To further investigate how HDAC4 can influence the TME in a cohort of melanoma patients who were pretreated with ICIs, we utilized the melanoma (MSK, NEJM 2014) dataset from cBioPortal." (PMID 40361444, 2025). "While a few studies have used in vitro and in vivo melanoma models to determine the effects of pan-HDAC inhibitors, the impact of HDAC4 in melanoma patients has remained elusive." (PMID 40361444, 2025). "They demonstrated expression of HDAC4, MTOR, PLK2, and ABCC1 to be affected in all melanoma cell lines tested." (PMID 28417283, 2017). "By contrast, HDAC4 and DOCK8 are in pathways that have not been implicated as important to nevogenesis or melanoma pathogenesis." (PMID 30429480, 2018). "In a bivariate analysis combining the nevus results with a recent melanoma GWAS meta-analysis (12,874 cases, 23,203 controls), SNPs near GPRC5A, CYP1B1, PPARGC1B, HDAC4, FAM208B, DOCK8, and SYNE2 reached global significance, and other loci, including MIR146A and OBFC1, reached a suggestive level." (PMID 30429480, 2018). "Analyzing the co-expression profile of the SKCM from the TCGA dataset, we found that HDAC4 expression was negatively correlated with the T-cell inflamed TME gene signatures across the sample population, indicating an inverse relationship between these gene sets in melanoma patients." (PMID 40361444, 2025). "While several HDAC inhibitors have been tested in combination with ICIs, such as anti-PD-1 and anti-CTLA4 therapy against multiple advanced-stage solid tumors, to the best of our knowledge, the effects of HDAC4 inhibitors with ICIs have not been reported, particularly in melanoma patients." (PMID 40361444, 2025). "We have highlighted eight novel loci, including the genes HDAC4, SYNE2, and most notably GPRC5A, where quite large samples of melanoma cases or nevus count were not sufficiently powerful to reach formal genome-wide significance in univariate analyses, but the combined evidence is conclusive." (PMID 30429480, 2018).
osteoarthritis (14 papers, 2014 to 2025). A noninflammatory degenerative joint disease occurring chiefly in older persons, characterized by degeneration of the articular cartilage, hypertrophy of bone at the margins and changes in the synovial membrane. "WJ-MSCs from IUGR individuals displayed a poor capacity of chondrogenic differentiation and an increased susceptibility to osteoarthritis-like phenotype, which was attributed to the decreased H3K9ac level of TGFβRI and its expression induced by high cortisol through GR/HDAC4." (PMID 33663609, 2021). "Exogenous administration of the histone deacetylation 4 (HDAC4) protein can effectively delay osteoarthritis (OA) progression." (PMID 39428562, 2024). "Histone deacetylase 4 was reduced in patients with AS compared with HCs and patients with osteoarthritis (both P < 0.01)." (PMID 35602496, 2022). "Meanwhile, serum HDAC4 was detected in 30 patients with osteoarthritis and in 30 healthy controls (HCs) by ELISA." (PMID 35602496, 2022). "Thus, all of these data suggest a different expression and role of HDAC4 depending on the stage of osteoarthritis." (PMID 36733912, 2023). "The aim of this study was to evaluate whether histone deacetylase 4 S246/467/632A mutant (m-HDAC4) has enhanced function at histone deacetylase 4 (HDAC4) to attenuate cartilage degeneration in a rat model of osteoarthritis (OA)." (PMID 34980076, 2022). "Notably, it has been reported that miR-365-3p negatively regulated histone deacetylase 4 (HDAC4) to stimulate primary chondrocyte proliferation and differentiation in mouse and chicken and to contribute to osteoarthritis pathogenesis in humans." (PMID 33431058, 2021). "It has been reported that HDAC4 is decreased in osteoarthritis cartilage, which may contribute to the pathogenesis of osteoarthritis cartilage degeneration." (PMID 27009967, 2016). "Finally, the HDAC4 enzyme, which plays a crucial role during skeletogenesis by inhibiting Runx2, notably as a target of PTHrP, also appears to be involved in the pathogenesis of osteoarthritis with different effects depending on the stage of the pathology." (PMID 36733912, 2023). "The present study evaluated whether the lack of histone deacetylase 4 (HDAC4) increases endoplasmic reticulum stress-induced chondrocyte apoptosis by releasing activating transcription factor 4 (ATF4) in human osteoarthritis (OA) cartilage degeneration." (PMID 38879481, 2024).
pancreatic cancer (13 papers, 2012 to 2026). "Together, these results found a ALKBH5/HDAC4/HIF1α positive feedback loop for cellular response to hypoxia in pancreatic cancer." (PMID 37149664, 2023). "Conversely, knockdown of endogenous HDAC4 facilitated HIF1α protein degradation in hypoxic pancreatic cancer cells." (PMID 37149664, 2023). "In this study, we decided to systematically investigate the function of HDAC4 in pancreatic cancer under hypoxia." (PMID 37149664, 2023). "A necroptosis-relevant risk model was developed for predicting pancreatic cancer survival and responses to immuno- and chemotherapy, comprising MYEOV, HDAC4, TLDC1, PITPNA, FNDC3B, HMGXB4, and BAX." (PMID 35662734, 2022). "In addition, HDAC4 functioned as an oncogene to maintain hypoxia-induced proliferation, migration and glucose metabolism in pancreatic cancer cells dependent m6A modification." (PMID 37149664, 2023). "Therefore, ALKBH5, HDAC4 and HIF1α form a positive feedback loop in PC cells under hypoxic conditions and contribute to pancreatic cancer progression." (PMID 37149664, 2023). "Emerging evidence also indicates that HDAC4 mediates smoking-induced pancreatic cancer metastasis." (PMID 37149664, 2023). "Taken together, HDAC4 maybe the key gene involved in hypoxia-induced pancreatic cancer cell metastasis and glycolytic metabolism." (PMID 37149664, 2023). "Congruently, in this study, we aimed to demonstrate whether HDAC4 could enhance the stability of HIF1a in hypoxic pancreatic cancer cells." (PMID 37149664, 2023). "HDAC4 correlates with the proliferative capacity and metastases of pancreatic cancer." (PMID 35662734, 2022). "Hypoxia triggers a feed-forward circuit in pancreatic cancer where the m6A demethylase ALKBH5, through demethylating HDAC4 mRNA, enables HDAC4-mediated stabilization of HIF1α." (PMID 41522342, 2026). "In pancreatic cancer, circCGNL1 enhances the interaction of the phosphatase NUDT4 and histone deacetylase 4 (HDAC4), promoting HDAC4 dephosphorylation and nuclear translocation to modulate gene expression." (PMID 41049614, 2025). "Our assays also demonstrated that hypoxia-induced HDAC4 enhanced HIF1a protein stability, and overexpressed HIF1a promoted transcription of ALKBH5 in hypoxic pancreatic cancer cells." (PMID 37149664, 2023). "BAX, FNDC3B, HDAC4, HMGXB4, MYEOV, and TLDC1 displayed upregulated expressions in pancreatic cancer than normal tissues." (PMID 35662734, 2022). "Recent reports show that histone deacetylase 4 (HDAC4) regulates HIF-1α protein acetylation and stability and ALKBH5 regulates m6A-modification of HDAC4 transcripts under hypoxic conditions in pancreatic cancer cells." (PMID 38227578, 2024). "No relevant data have been reported for HDAC-4, while high HDAC-6 expression has been emerging as a favorable prognostic factor in terms of survival in invasive breast and pancreatic cancer." (PMID 33799478, 2021).